ENSG00000273398 (novel protein)
Gene: Protein-coding gene on chromosome 2 (68,131,238 to 68,261,230, reverse strand). Ensembl gene ENSG00000273398.
Genetic constraint (gnomAD): Missense variants: 152 observed, 266.06 expected, observed/expected ratio (o/e) 0.57, 90% interval 0.5 to 0.65. Synonymous variants: 87 observed, 99.33 expected, observed/expected ratio (o/e) 0.88, 90% interval 0.74 to 1.05.